IGF1 (insulin like growth factor 1)
Diseases named in the same sentence as IGF1 in open-access papers (continued):
Sharing a sentence is not in itself a finding about the gene and the disease.
Hepatic steatosis (69 papers, 2010 to 2026). Steatosis is a term used to denote lipid accumulation within hepatocytes. "In summary, the GH/IGF-1 axis has a crucial role in metabolic and endocrinal pathways of liver steatosis while IGF-1 deficiency is established as a co-factor to this syndrome." (PMID 39781288, 2025). "GH deficiency predisposes patients to hepatic steatosis while IGF-1 and T3 deficiencies leave the liver more vulnerable to oxidative damage." (PMID 40416908, 2025). "While GH deficiency predisposes patients to hepatic steatosis, IGF-1 deficiency leaves the liver more vulnerable to oxidative damage." (PMID 40416908, 2025). "To extend understanding of the determinants of hepatic steatosis, we next evaluated associations between liver fat fraction and inflammatory cytokines and IGF-1." (PMID 40700400, 2025). "A cross-sectional study suggested that IGF-1 deficiency was positively associated with NAFLD (defined using a validated hepatic steatosis index) in patients with PitNET." (PMID 38370349, 2024). "Experimentally, hepatic steatosis-related alterations in GH/IGF-1 axis are associated with a decrease in muscle myofibrillar protein content and a reduction in muscle strength in the absence of significant inflammation." (PMID 30200408, 2018). "Last, insulin-like growth factor-1, which is associated with hepatic steatosis, inhibits apoptosis and promotes progression through the cell cycle, and may play a role in pancreatic carcinogenesis." (PMID 35739172, 2022). "Others confirmed that IGF1 levels were negatively associated with hepatic steatosis." (PMID 29702590, 2018). "We also revealed that a lower IGF-1/IGFBP-3 ratio might cause more advanced hepatic steatosis in patients with HCV-related CLD." (PMID 29342898, 2018). "Mild liver steatosis may be accompanied by disruptions in crucial liver function markers, notably those implicated in iron metabolism, autophagy, and growth factor regulation, such as IGF-1." (PMID 39976226, 2025). "However, increasing evidence is showing the association of low circulating GH levels and IGF1 levels with hepatic steatosis, and inactivating mutations in the GHR of mice resulted in hepatic steatosis due to enhanced lipogenesis and reduced TG secretion from the liver." (PMID 36296646, 2022). "Low IGF-1 levels contribute to metabolic dysfunction, as IGF-1 has insulin-sensitizing and anti-inflammatory properties that protect against hepatic steatosis and fibrosis." (PMID 40520449, 2025). "The GH/IGF-1 metabolic pathway has correlated with hepatocyte triglyceride secretion, liver steatosis, and fibrosis progression." (PMID 39781288, 2025). "The association between serum levels of GH, IGF-1, and IGF-binding protein 3 (IGF-BP3) and hepatic steatosis and fibrosis in patients with NAFLD has been reported, even among individuals without GH deficiency." (PMID 38836220, 2024). "After administering rhGH to hypophysectomized rats, the JAK2-STAT5B signaling pathway activated with evidence of restoration of circulating IGF-1 levels, growth promotion and metabolic effects of alleviation of fatty liver." (PMID 38836220, 2024). "Routine laboratory examinations, BMI, liver steatosis indices, liver CT attenuation, ferritin, and IGF-1 serum levels were assessed and correlated with severity." (PMID 36851702, 2023). "In this regard, mRNA levels of hepatic IGF-1 obviously decreases in NASH patients in comparison to patients with liver steatosis and predicts the degrees of hepatic inflammation." (PMID 36419770, 2022). "We further show that IGFBP2 blunts the stimulation of de novo lipogenesis by IGF1 in hepatocytes from healthy mice or mouse models with fatty liver disease." (PMID 32532003, 2020). "In order to characterize hepatocytes responding to IGF-1 overexpression in CCl4-induced hepatic steatosis and fibrosis, we detected oxidation and aging-related markers in purified primary hepatocytes, which isolated from rat model livers." (PMID 31171766, 2019).
Hepatic steatosis (continued). "Argentinian studies also showed that IGF1 levels decreased with progression of liver steatosis in NAFLD patients." (PMID 29702590, 2018). "In line with this, studies showed reduced growth hormone/insulin-like growth factor-1 (GH/IGF-I) levels, which induce hepatic steatosis, in ALS21,36." (PMID 27785351, 2015). "Chronic hepatitis C virus (HCV) infection may influence cytokine and insulin-like growth factor (IGF-1) levels, which could contribute to increased hepatic steatosis." (PMID 40700400, 2025). "Modulates GH/IGF-1 axis for muscle growth and reduced liver steatosis." (PMID 39796612, 2025). "Subsequent studies have shown that IGFBP2 blunts the stimulation of de novo lipogenesis by IGF1 in hepatocytes from healthy mice or mouse models with fatty liver disease, suggesting that lower levels of IGFBP2 may exacerbate the development of MASLD." (PMID 40608848, 2025). "Altogether, the GH/insulin-like growth factor-1 axis plays an essential role in preventing hepatic steatosis aggravation in fatty liver disease, which may ameliorate the respiratory symptoms in HPS." (PMID 39502571, 2024). "Besides, some studies showed that NAFLD is associated with low IGF-1 levels and IGF-1 levels are an independent prognostic factor for liver steatosis and NASH." (PMID 38492309, 2024). "However, only a few clinical studies have explored the potential link between SARS-CoV-2 infections and the growth hormone (GH)/insulin-like growth factor–1 (IGF-1) axis and between liver steatosis and COVID-19 severity." (PMID 36851702, 2023). "However, GH, IGF-1, insulin-like growth factor binding proteins (IGFBPs), and medical treatment have a complex relationship with insulin sensitivity and hepatic steatosis." (PMID 35448486, 2022). "Moreover, based on the evidence from animal studies, lower IGF-1 levels are associated with lower protection against IR, inflammation and liver steatosis, while, treatment with IGF-1 improves liver enzymes, steatosis and fibrosis." (PMID 36419770, 2022). "Furthermore, in a diet-induced NAFLD mouse model, the GH and IGF-1 supplementation induced a significant improvement in liver steatosis and inflammation." (PMID 31540048, 2019). "IGF-1 supplementation reverted liver steatosis induced by HFD at histology analysis." (PMID 29724029, 2018). "It is consistent with study where low levels of Igf1 were found in sera of patients with hepatic steatosis and this association was independent of alcohol consumption." (PMID 26604919, 2015). "IGFBP2 may also influence hepatic steatosis through its interaction with IGF1." (PMID 40608848, 2025). "While the reduced levels of circulating growth hormone (GH) and insulin-like growth factor 1 (IGF-1) have been consistently observed in patients with hepatic steatosis, the molecular role of hepatic growth hormone receptor (GHR) in MAFLD pathogenesis remains unclear." (PMID 41847434, 2025). "In experimental studies in fatty liver-induced models, the animals had decreased levels of IGF-1, while opposite animals treated with GH and IGF-1 had reduction of liver triglycerides and transaminases." (PMID 39781288, 2025). "Change in IGF-1 was correlated with improvements in NAS (r = -.547; P = .019) and NASH score and the reduction of hepatic steatosis measured by MRI." (PMID 40520449, 2025). "In this regard, GH/IGF-1 axis is involved in the progression of NAFLD and predicts liver steatosis/fibrosis." (PMID 36419770, 2022). "Hepatic steatosis is, in part, regulated by JAK-STAT signaling – in particular, through its effect on the insulin-like growth factor-1 (IGF-1)/growth hormone axis." (PMID 34109302, 2021). "In the present study, we have shown that long-term DHEA feeding reduced both serum IGF-1 and IGFBP-3 levels, which potentially can be effective in reducing liver steatosis." (PMID 28335515, 2017). "Mechanistically, IGFBP2 inhibits IGF1 activation on DNL, and the reduction of IGFBP2 may, therefore, aggravate the development of fatty liver disease." (PMID 32532003, 2020).
Hepatic steatosis (continued). "Low hepatic GH levels may lead to the development of hepatic steatosis in patients with NAFLD, whereas low serum IGF-1 levels contribute to fibrosis." (PMID 20653983, 2010).
ischemic stroke (67 papers, 2010 to 2025). A stroke disorder caused by obstruction of blood flow to the brain, due to thrombotic (local blood clot formation) or embolic (due to a blood clot or other material traveling from another site) event. "A meta-analysis further linked elevated TNF-α with reduced IGF-1 as joint risk factors for ischemic stroke." (PMID 41393761, 2025). "In clinical studies, lower IGF-1 levels have been associated with poorer outcomes after ischemic stroke, although findings vary according to baseline patient factors." (PMID 41586110, 2025). "Unlike previous individual studies, our meta-analysis simultaneously evaluates IGF-1 in relation to both ischemic stroke risk and long-term functional prognosis, with subgroup analyses based on follow-up duration." (PMID 41586110, 2025). "A recent meta-analysis consisting of 2,277 patients from 17 studies revealed that a higher serum IGF-1 concentration was significantly associated with a lower risk of ischemic stroke." (PMID 37608387, 2023). "Using qPCR, we successfully validated several key genes regarding CD11c-associated molecules (Itgax, Gpnmb, Gpx3, Csf1, Spp1, Igf1) in the sham group, Day 7, Day 14, and Day 30 after ischemic stroke." (PMID 36828819, 2023). "Higher serum IGF-1 levels just after ischemic stroke onset are associated with a better neurological and functional outcome." (PMID 37358957, 2023). "Several epidemiological studies including the Framingham Study have shown that low baseline circulating IGF-1 is associated with an increased risk of ischemic stroke." (PMID 36979670, 2023). "Patients with higher serum IGF-1 were significantly associated with a lower risk of ischemic stroke." (PMID 36569944, 2022). "Understanding the mechanism by which IGF-1 levels fluctuate in patients with OSAHS is critical because studies have shown that lower IGF-1 levels increase the risk of cardiovascular events following ischemic stroke and coronary intervention." (PMID 36120463, 2022). "Clinical and preclinical evidence highlight inverse correlation (and causation in animal models) between IGF-1 and the risk/outcome of ischemic stroke." (PMID 34887742, 2021). "It was reported that elderly AF patients show low level of serum IGF-1 level, and low level of circulating IGF-1 was associated with risk of ischemic stroke in AF patients, especially in diabetic and obese patients." (PMID 32244749, 2020). "Lower IGF-1 levels are significantly related to risk of ischemic stroke occurrence, independent from other conventional risk factors in the Egyptian population." (PMID 30595648, 2018). "Another study published by Hamidreza and colleagues showed that circulating IGF-1 levels were associated with risk of ischemic stroke, with subjects in the lowest quintile of IGF-1 levels having a 2.5-fold higher risk of incident ischemic stroke." (PMID 30595648, 2018). "A reduced serum IGF-1 level was an independent risk factor for ischemic stroke with cut off value less than 148.3 ng/ml associated with increased AIS risk." (PMID 30595648, 2018). "For example, elderly patients with low circulating IGF-1 levels are at a much higher risk of ischemic stroke and congestive heart failure." (PMID 26467524, 2015). "Neurogenesis, particularly IGF-1-mediated neurogenesis, is a major mechanism underlying beneficial effects of exercise on ischemic stroke." (PMID 23565939, 2013). "This systematic review and meta-analysis suggests that oxidative stress-related IGF-1 may be associated with long-term unfavorable outcomes following ischemic stroke, particularly beyond 1 year after onset." (PMID 41586110, 2025). "Research findings suggest that IGF-1 is associated with the risk of ischemic stroke, and low circulating IGF-1 may be a particularly important determinant of ischemic stroke events in obese and diabetic patients." (PMID 39963470, 2025).
ischemic stroke (continued). "This meta-analysis suggests that oxidative stress-related IGF-1 may be associated with long-term unfavorable outcomes in patients with ischemic stroke, especially beyond 1 year after symptom onset." (PMID 41586110, 2025). "Furthermore, a few studies found that lower IGF-1 levels are associated with increased risk of ischemic stroke, and higher IGF-1 levels after ischemic strokes are associated with better functional recovery." (PMID 39119013, 2024). "IGF-1, expressed in the CNS by microglia/macrophages, astrocytes, and neurons, enhances axon outgrowth of corticospinal motor neurons in vitro and in the developing CNS, and high serum IGF-1 levels just after the onset of ischemic stroke are associated with better neurological recovery in humans." (PMID 36995772, 2023). "Higher IGF-1 levels are associated with a lower risk of incident ischemic stroke." (PMID 37358957, 2023). "It has been reported that unilateral manual needling on limb muscles resulted in modulatory effects in human brain as shown in functional MRI, and electroacupuncture caused bilateral changes in the insulin-like growth factor (IGF-1) mRNA and protein in rat brain of an ischemic stroke model." (PMID 35139128, 2022). "Considering glutamate excitotoxicity is one of the main drivers of neurodegeneration following ischemic stroke, the age-related loss of IGF-1 may also compromise neural function indirectly by altering the function of supporting glia and vasculature." (PMID 34887742, 2021). "Physical inactivity, a condition accumulated in long-lasting RA and in ischemic stroke, is frequently associated with lower serum IGF1 that could be increased with physical exercise." (PMID 31327319, 2019). "Their results suggest that IGF-1 is related to risk of incident ischemic stroke and support an emerging hypothesis that low circulating IGF-1 may be an important determinant of ischemic stroke events." (PMID 30595648, 2018). "Experimental studies have demonstrated that delayed IGF-1 administration can reduce hypoxia-ischemia-induced neuronal damage and improve behavioral recovery in immature and adult ischemic stroke models." (PMID 41586110, 2025). "IGF-1 remains a promising prognostic biomarker, but its role as a therapeutic target for ischemic stroke recovery has yet to be confirmed." (PMID 41586110, 2025). "Upon ischemic stroke, microglia up‐regulate Trem2 expression levels, which subsequently boosts Igf1 expression and affects microglial metabolic profiles as well as cellular functions." (PMID 38151703, 2024). "Conclusively, the transcriptional profiles of microglia suggested increased frequency of a subcluster during ischemic stroke, with molecular signature of upregulated Trem2 and Igf1, and functional features of neuroprotective and pro‐repairing properties." (PMID 38151703, 2024). "Our observations are in line with previous reports showing that IGF1/IGFBP1 intranasal delivery is protective after ischemic stroke." (PMID 38769116, 2024). "Gene variants in Igf1, Igf1r and GHRH are associated with protection against the development of ischaemic stroke." (PMID 39595651, 2024). "In the present study, we first identified a microglial subcluster up‐regulated after ischemic stroke, characterized by enhanced OXPHOS and a molecular signature of upregulated Trem2, Igf1, as well as other phagocytosis‐associated molecules." (PMID 38151703, 2024). "This suggests that reactive PDGFRβ+ pericytes contribute to IGF1 production at the lesion site after ischemic stroke." (PMID 38769116, 2024). "In an ischemic stroke rat model, IGF-1 plays multiple roles in increasing sensorimotor function, improving cognitive function, and reducing infarct size." (PMID 36569944, 2022). "Clinically, several studies have shown that reduced levels of IGF-1 in human patients correlated with increased mortality rate, poorer functional outcomes, and increased morbidities following an ischemic stroke." (PMID 35203315, 2022).